RAG1 (recombination activating 1)
Diseases named in the same sentence as RAG1 in open-access papers (continued):
Sharing a sentence is not in itself a finding about the gene and the disease.
infection (continued). "In a similar manner, reconstitution of Rag1-/- mice with CD4 T cells that overexpress IFN-γ induces pulmonary pathology and exacerbates bacterial burden in the lung while controlling infection outside of the lungs." (PMID 35877763, 2022). "To establish the immune cell population(s) involved in restricting VACV∆C7L infection, we first performed intranasal infection of VACV∆C7L in WT and Rag1−/− mice, which lack mature T and B cells." (PMID 35351885, 2022). "We then compared the abundances of the major phyla in Rag1–/–, NSG, and wild-type mice at different times post infection." (PMID 34445184, 2021). "Following infection, IFN-β mRNA was transiently increased in the spleen of WT, STAT1 KO and STAT1/RAG1 DKO mice on day 3 postinfection and was undetectable at day 7 postinfection." (PMID 32310998, 2020). "In this work, we wanted to take advantage of this model to study lncRNA profiles after early infection with SVCV in both WT and rag1+/− zebrafish." (PMID 31578442, 2019). "Next, to test whether infection-induced parasite-specific IgG could potentially bind internal parasite structures exposed during schizont rupture, we fixed and permeabilised pRBC (from either WT or rag1-/- passage mice) in vitro prior to exposure to immune serum." (PMID 30811498, 2019). "Interestingly, Venn diagrams showed that the majority of these transcripts were exclusively modulated after infection in each line, with 5,461 coding RNAs and 593 lncRNAs being exclusively modulated in WT and 3,653 coding RNAs and 250 lncRNAs being exclusively modulated in rag1+/− zebrafish." (PMID 31578442, 2019). "How these cells get activated in the infection of CB17 SCID and C57BL/6 RAG1−/− mice, however, is unclear." (PMID 28770333, 2017). "To examine what effect IFN suppression and deficiency of the adaptive immune response had on VTx following peripheral infection, we infected female AIR mice impregnated by Rag1−/− males with ZIKV at 7 dpm." (PMID 28775298, 2017). "In C57BL/6 mice, and similarly in Rag1−/− mice, ST2+ILC2 cells decreased early in infection to return to baseline level 10 days later while CD25+ILC2 stably decreased." (PMID 28090087, 2017). "We also show that Hirep1-induced neutralizing antibodies can adoptively transfer protection into Rag1 knockout (KO) mice, which emphasizes the role of antibodies without the involvement of CMI responses in the early control of infection with C.t." (PMID 29312283, 2017). "Rag-1−/− mice infected with ST or ST-OVA (103, iv) succumbed to the infection suggesting that T cell response is required for protection against ST." (PMID 27599659, 2016). "This damage is delayed in RAG1-/- compared to C57BL/6J mice, although the muscle damage seen by day 14 post infection is comparable in the two strains." (PMID 26115459, 2015). "Wild-type RB50 induced lower levels of IL-1β than RB50ΔclpV in the lungs and spleens of Rag1-/- mice by day 21, indicating that the T6SS suppresses IL-1β production during infection (p<0.05)." (PMID 26485303, 2015). "Considering that CD4+ T cells are required for the increased IEC proliferative response during infection, we tested if Rag1-/- mice were impaired in RELM-β production, but instead found it was strongly expressed in their colons during infection." (PMID 26285214, 2015). "In both B6 and RAG1−/− recipient mice, passive transfer of serum from MNV-3-infected mice provided significant protection from MNV-3 and MNV-1 infections in the distal ileum, colon, and MLNs." (PMID 24039576, 2013). "The results were essentially identical in RAG1−/− mice depleted of NK cells by continuous treatment with anti-Asialo-GM1 antibodies before and after infection with MCMV viruses." (PMID 23271968, 2012). "In contrast, Mono/Mac1 was present in both WT and Rag1–/– mice at day 3 but was nearly absent in WT animals by day 7 after infection." (PMID 39989461, 2025). "Following inoculation, both Stat1 and Rag1 KO mice showed no clinical signs of infection or mortality." (PMID 40304490, 2025).
infection (continued). "Although bacterial burdens were significantly reduced in Rag1–/– mice receiving Th1 or Th17 cells at day 3, delaying adoptive transfer until day 7 after infection failed to prevent S. aureus outgrowth." (PMID 39989461, 2025). "Examination of monocyte and macrophage transcriptional profiles revealed the appearance of a macrophage/monocyte cluster (Mono/Mac2) at day 7 after infection in WT animals that was largely absent in Rag1–/– mice." (PMID 39989461, 2025). "Since B cells are not efficiently recruited to the spinal cord following EV-D68 infection, we anticipated that the delay in onset of paralysis of Rag1–/– mice was attributable to the absence of T cells." (PMID 40459936, 2025). "However, PMNs infiltrating the brain of Rag1–/– mice exhibited a mix of proinflammatory (LCN2, APOE) and antiinflammatory (WFDC21, RETNLG) molecules that was most prominent at day 7 after infection along with enhanced PD-1/PD-L1 pathway expression." (PMID 39989461, 2025). "Similar to microglia and monocytes/macrophages, the Dendritic 1 cluster in Rag1–/– mice had significant reductions in Type I and Type II IFN responses, IL-1 production, AIM2 inflammasome, and Ag presentation pathways primarily at day 7 after infection." (PMID 39989461, 2025). "Rag1−/− mice without adoptive transferred cells succumbed significantly later (around 20 days post infection) compared to RORγt−/− mice lacking ILC3s (6 days post infection)." (PMID 39504243, 2024). "Ns from orally infected mice was generally lower at all sites than during IV infections suggesting that passage through the intestinal barrier in mice lacking Rag1 comprises a very stringent bottleneck." (PMID 38635627, 2024). "Importantly, the adoptive transfer of mito‐transferred naïve CD4+ T cells from old mice into Rag1‐KO mice protected these mice against influenza A virus (IAV) and Mycobacterium tuberculosis (M.tb) infections." (PMID 37990641, 2024). "Independent of 4’-FlU dose level, all treated animals of the RAG-1 KO and IFNAR1 KO groups survived, whereas all animals in the vehicle-treated groups developed severe clinical signs and succumbed to infection within 4 days." (PMID 37068076, 2023). "We performed whole-tissue untargeted metabolomics on VACV-infected skin from our infection model (NPS or NPE infection of Rag1-/- mice) with and without adoptively transferred OT-I CD8+ T cells." (PMID 38009914, 2023). "Although the MEs of the Rag-1-/- mice receiving wild type splenocytes did not clear the primary infections even at day 56 p.i., they allowed long term experiments and observations to be made." (PMID 38125908, 2023). "Recombination activating gene-1 (RAG-1) mice have no mature T or B-cells, infections of these mice with influenza A virus resulted in death 14 days after infection." (PMID 34696520, 2021). "Splenectomised mice were able to control the infection to a low parasitaemia level, unlike Rag1 knockout mice lacking B and T cells, indicating that extrasplenic immune responses, possibly in the lymph nodes or the liver, contribute as well." (PMID 34532703, 2021). "In this short infection model, we repeated our finding that adaptive immunity is not necessary for protection, as both RAG1−/− and WT mice colonized with str." (PMID 33785619, 2021). "After challenge with ECTV, all Ifnar1-/-→ Rag1-/- mice quickly succumbed to infection whereas similar to Rag1-/- + B6 → Rag1-/-, most Rag1-/- + Ifnar1-/-→ Rag1-/- mice survived the infection with mild or no signs of disease." (PMID 34015056, 2021). "Increased virus RNA levels in the absence of STAT1 but not RAG1 on day 3 postinfection suggests that during the early stages of infection, IFN-Is rather than adaptive immune cells are critical for inhibiting initial virus replication and spread." (PMID 32310998, 2020).
infection (continued). "Thus, 667 isnot intrinsically attenuated and we conclude that adaptive immunity is criticalin controlling bacterial growth, most clearly observed by the change in relativeabundance between RAG1 KO and C57BL/6J mice, two- and three-weekspost-infection." (PMID 33075106, 2020). "In the liver following infection, NK cells, pDCs, CD8α+ DCs and CD8+ T cells were significantly increased in WT mice and NK cells, as were CD8α+ DCs and F4/80hi CD11blo macrophages in RAG1 KO mice." (PMID 32310998, 2020). "Notably, RAG1 KO mice exhibited a remarkable, STAT1-dependent capacity to control LCMV infection initially but this was ineffective as infection progressed." (PMID 32310998, 2020). "Looking at the fish with a sustained infection (unable to clear the infection), HKLm priming reduced the bacterial load in rag1 mutants by 7.2-fold (not statistically significant)." (PMID 29208761, 2018). "In order to determine whether KSHV-associated BCR revision was Rag-mediated we performed nested RT-PCR for Rag transcripts and were able to detect both RAG1 and RAG2 mRNA at early time points post-infection." (PMID 29659614, 2018). "Control experiments in an A431 cell culture indicated that there the adapter is stable in Rag1-/- mice serum, since preincubation of adapter in serum had no significant impact on infection efficacy." (PMID 29386504, 2018). "IFN-γ and IL-6 levels were higher in some Rag1−/− mice that received peritoneal B cells than mice that did not 14 d post-infection." (PMID 28837391, 2018). "On day 14 post-infection, CFU in the lungs were similar between Rag1−/− and wild-type mice." (PMID 28837391, 2018). "Some Rag1−/− mice that received B cells also had higher levels of IFN-γ than mice that did not receive B cells 14 d post-infection, but this was not the case for every mouse and CFU were not determined in the same mice." (PMID 28837391, 2018). "In brief, infection of the CNS of RAG1-/- mice (lacking functional T and B lymphocytes) with the CXCL10-expressing recombinant virus resulted in protection from disease associated with increased infiltration of NK cells into the CNS." (PMID 30577473, 2018). "As with Rag1 KO mice, the infection history of the muMT- blood-meal host had no impact on the pathogenic potential of spirochetes in fed ticks." (PMID 29621350, 2018). "rag1 mutant zebrafish, which lack lymphocytes, also form noncaseating granulomas with similar kinetics, but these control infection more slowly." (PMID 28934421, 2017). "Peak production of IL-9 was also observed in Rag1−/−, and less in Rag1−/−/Il9R−/−, mice early but not late in infection, a finding suggesting that early IL-9 production is IL-9R-dependent and late is T-cell-dependent." (PMID 28090087, 2017). "At 112 days after infection and 168 days after infection, 2 of 3 rag1 heterozygotes contained no bacilli, while 1 of 3 rag1 mutants contained no bacilli." (PMID 28934421, 2017). "Second, we performed adoptive T cell transfer into R. typhi-infected C57BL/6 RAG1-/- mice to show whether CD8+ and CD4+ T cells would still be protective in an established R. typhi-infection." (PMID 27875529, 2016). "The muscle and footpad recover in RAG1-/- mice, just as in C57BL/6J mice, by day 28 post infection." (PMID 26115459, 2015). "Despite damage in the ipsilateral skeletal muscle of the leg at day 14, no infectious virus was isolated beyond day 28 post-infection in RAG1-/- mice." (PMID 26115459, 2015). "Rag1-/- mice inoculated with either RB50 or RB50ΔclpV were thus assessed for bacterial numbers in the respiratory tract (nasal cavity, trachea, and lungs) or systemic organs (liver and spleen) 21 days post-infection." (PMID 26485303, 2015). "We found that Rag1−/− mice and RAG+CD8 mice had similar numbers of parasites at the infection site, in spite of the disparity in lesion size observed in these animals, while transfer of CD4+ and CD8+ T cells into Rag1−/− mice led to significantly better control of the parasite in the infected ear." (PMID 23874205, 2013).
infection (continued). "Our adoptive transfer study supports this since purified CD4+ T cells were able to mediate partial protection to a MNV-3 primary infection even when recipient mice lacked other adaptive immune cells (i.e. RAG1−/− recipients)." (PMID 24039576, 2013). "Why does the RB50ΔsigE mutant spread systemically and cause lethal infection in TLR4def and TNF-α−/− mice, but not Rag1−/− mice?" (PMID 22897969, 2012). "Adoptive transfer of Bcl10-/- CD4+ T cells prior to infection partially restored worm growth, resulting in a phenotype that was intermediate between RAG-1-/- recipients of wild type CD4+ T cells and non-reconstituted RAG-1-/- mice." (PMID 20442785, 2010). "Rag1–/– mice did not display motor abnormalities following Th1 or Th17 adoptive transfer, suggesting that autoimmune-like pathology does not manifest during craniotomy infection during the timescale examined in this study." (PMID 39989461, 2025). "Blocking both integrins significantly reduced CD4+ and CD8+ T cell recruitment to the brain at day 7 after infection, resulting in higher infectious burdens compared with isotype-treated mice concomitant with increased G-MDSC and PMN influx, resembling phenotypes in Rag1–/– animals." (PMID 39989461, 2025). "Together, these results suggest that a lack of clearance of OMP parasites in Rag1−/− mice ultimately promoted a ~10-fold expansion of OMP parasites in the peritoneal cavity after 12 days of infection due to the ability of OMP to replicate at a very slow rate in low uracil concentration environments." (PMID 39440975, 2024). "Notably, Rag1−/− mice that received either WT or RORγtK256R/K256R CD4+ T cells all survived and exhibited similarly low bacterial loads 20–25 days post infection, supporting effective Th17 responses against infection." (PMID 39504243, 2024). "The use of Rag1 KO mice enables infection in a context where pathogen clearance is not achieved." (PMID 38635627, 2024). "Rag-1-/- mice not given wild type spleen cells succumb to infection before day 21, so could not be included for comparison." (PMID 38125908, 2023). "In addition to the determination of the tissue distribution of all crp transcripts and their modulation after infection with the spring viremia of carp virus (SVCV), they were also analyzed on the skin from zebrafish that are mutants of recombinant activation gene 1 (rag1+/+ and rag1−/−)." (PMID 33498981, 2021). "Despite cohabitation and continuous microbial exposure from FMT-treated C57BL/6 mice, FMT-treated Rag1−/− mice exhibited significantly higher C. difficile burden and toxin titers in the feces compared to C57BL/6 mice in the context of either a CD196 strain infection or VPI10463 strain infection." (PMID 33531483, 2021). "The spleen however is not the only organ involved in protective immunity as splenectomised mice still are able to control infection albeit at a higher parasitaemia levels, unlike Rag1 knockout mice, indicating that other lymphoid organs such as lymph nodes and liver also play a role." (PMID 34532703, 2021). "Thus, the relative expansion of strictly anaerobes through the course of the infection likely limited the expansion of Proteobacteria in Rag1–/– mice as opposed to NSG mice." (PMID 34445184, 2021). "infection of rag1-/- mice, lacking mature T and B cells, and WT controls was then compared." (PMID 34587172, 2021). "Northern blot analysis showed that infection with either NoVΔB2 or NoVmB2 induced production of vsiRNAs in Stat1/2−/− adult mice at levels comparable to that in C57BL/6 mice, which accumulated markedly reduced levels of vsiRNAs compared to that in Rag1−/− mice." (PMID 32753500, 2020). "Similarly to that with NoV infection of Rag1−/− mice, vsiRNAs were undetectable by Northern blotting in NoV-infected Stat1/2−/− mice." (PMID 32753500, 2020).
infection (continued). "Consequently, piglets carrying homozygous RAG1, RAG2, or IL2RG mutations (A632-2, A632-1), which looked normal and strong upon birth, died 12 and 49 days after birth, respectively, due to infection in the lung." (PMID 31253764, 2019). "The importance of the immune system in driving demyelination in JHMV-infected mice is further emphasized by the demonstration that infection of RAG1-/- mice does not result in demyelination even though viral replication in resident glial cells, including oligodendroglia, is unrestricted." (PMID 30577473, 2018). "Indeed, previous work from our group demonstrated that Rag1-/- animals, lacking T and B cells, control the fungus and recover from infection within a week." (PMID 29782555, 2018). "IgM was also detectable in the lungs of wild-type and Rag1−/− mice that received B cells, but levels were significantly higher in the wild type C57Bl/6 mice.Lung IgM and serum GXM-IgM were also detectable 14 d post-infection in mice that received peritoneal B cells." (PMID 28837391, 2018). "It is important to remark that though Rag1-/- mice have no mature T and B lymphocytes, develop totally normal granulocytes, like WT mice, as has been demonstrated in reports which use these mice in infection models." (PMID 29875750, 2018). "At day 13 post infection, we observed a complete rescue of the virus titer in spleen, lungs, and salivary glands, strongly arguing that the inhibition of death-receptor apoptosis is required for MCMV replication in RAG1−/− mice, and MCMV virulence in immunocompromised hosts." (PMID 23271968, 2012). "Transcription levels of the myeloid-associated genes C/EBPα, PU.1, FOG1, and G-CSF were increased in total BM cells by 2–3-fold at 12 h post infection, while transcription levels of the lymphoid-associated genes IL7-R, Flt3, Rag1, PAX5, and Ikaros did not change at this time point." (PMID 23189271, 2012). "Additionally, while WT mice presented a strictly localized infection with no viral replication in evaluated internal organs, Rag1−/− had an extensive replication in spleen and ovaries at both analyzed time points (p<0.05, one sample t test)." (PMID 21526210, 2011). "Whereas all RAG1−/− mice inoculated with blood or brain homogenates from suramin-treated mice showed parasites early after infection, no parasites were detected in mice inoculated with either blood or brain homogenates from cordycepin- and deoxycoformycin-treated mice." (PMID 19652702, 2009). "Therefore, reduced monocyte-derived cell recruitment in Rag1−/− mice might reduce pathogen proliferation at early phases of infection and thus compensate for the lack of iNOS-mediated killing." (PMID 34687607, 2021). "A myeloid cell flow cytometry panel was established and optimised for the infection model using C57BL/6 and Rag-1-/- mice infected via non-invasive intratracheal inoculation with 1x103 yeast cells/ 50 μl." (PMID 38198478, 2024). "In the immune-competent Rag-1+/+ mice, however, we did not see any increase in DCLK1 levels in response to CR infection compared to uninfected controls (2.57 vs. 2.44%) (data not shown)." (PMID 34226497, 2021). "In contrast to the early timepoints postinfection, during late stages of infection, LCMV RNA levels were increased in the absence of RAG1, independent of STAT1." (PMID 32310998, 2020). "Lung CFU were comparable in wild-type, Rag1−/−, and Rag1−/− mice that received B cells 21 d post-infection, but brain CFU were significantly lower in mice that received B cells than Rag1−/− mice that did not." (PMID 28837391, 2018). "On day 21 post-infection (28 d after adoptive transfer), lung CFU of Rag1−/− mice that received naïve splenic B cells were comparable to those of Rag1−/− that did not receive B cells and wild-type mice." (PMID 28837391, 2018). "To test the effect of infection on T cells with specificity for non-schistosome antigens, we infected TCR-transgenic OT-II/RAG-1−/− mice that only possess OVA-specific CD4+ T cells." (PMID 23556020, 2013).